INS (insulin)
Diseases named in the same sentence as INS in open-access papers (continued):
Sharing a sentence is not in itself a finding about the gene and the disease.
Insulin resistance (continued). "It is unclear how excess adiposity and insulin resistance affect β cell function, insulin secretion, and insulin clearance in people with obesity." (PMID 34905513, 2022). "In T2DM, insulin resistance can be defined as a metabolic state with a relatively low insulin action (insulin sensitivity) compared to the normal state of physiological insulin concentrations." (PMID 35053962, 2022). "Hepatocyte insulin resistance promotes hyperglycemia and enhances more compensatory insulin production, which prompts DNL by activation of carbohydrate-response element binding protein (ChREBP) and sterol regulatory element binding protein-1c (SREBP-1c)." (PMID 36438731, 2022). "Insulin resistance is a common risk factor for both NAFLD and dementia, displaying increased insulin signaling-mediated cell death, impaired LTP, and imbalanced neurotransmitter secretion." (PMID 35765060, 2022). "Fasting plasma glucose (FPG) and fasting plasma insulin (FPI) were determined to calculate homeostatic model assessment insulin resistance (HOMA-IR)." (PMID 36246070, 2022). "Increased adiposity and adipocyte inflammation impair insulin signaling and contribute to the development of insulin resistance and metabolic dysfunction, which are characterized by the inhibition of the antioxidant genes PGC-1α and HO-1." (PMID 35740043, 2022). "Mice also developed insulin resistance as manifested by a 32% increase in fasting glucose levels and an almost 10-fold increase in fasting plasma insulin levels." (PMID 35964946, 2022). "After hUC-MSC infusion, the serum insulin level was significantly increased (P < 0.01), and there was an obvious decline in insulin resistance (P < 0.05)." (PMID 35414044, 2022). "HOMA - IR (Fasting plasma glucose (mmol/l) x plasma fasting insulin (m IU/ml)/22.5) was used to calculate insulin resistance HOMA-IR was considered high when it is HOMA-IR ≥ 2.69." (PMID 37654824, 2022). "Studies indicate that the functional and structural integrity of the central nervous system is altered in Type 2 DM due to insulin excess or insulin resistance." (PMID 35336756, 2022). "Type 2 diabetes, a condition involving insulin resistance and impaired insulin secretion that progresses to a chronic hyperglycemic state, is a leading cause of death worldwide." (PMID 36501092, 2022). "The GTT results showed that the STZ-treated mice showed significant glucose intolerance, and the ITT results indicated that these mice showed significant insulin resistance after insulin injection." (PMID 35420971, 2022). "The third subgroup (SIRD-RII, 19% of participants) is characterised by severe insulin resistance, poor glycaemic control and relative insulin insufficiency as indicated by preserved insulin secretion but a low HOMA2-B." (PMID 35763031, 2022). "The hypertrophic adipocytes and adipose tissues induce pre-inflammatory cytokines, such as tumor necrosis factor α (TNF-α), that prevent insulin signaling and lead to insulin resistance." (PMID 36387872, 2022). "A greater impairment in first-phase insulin secretion, indicative of hepatic insulin resistance (HIR), can be found in individuals with isolated IFG." (PMID 35327447, 2022). "Previous studies report that circulating TNFα interferes with insulin signaling through its receptor, while TNFα knockout mitigates insulin resistance in obese mice." (PMID 36559697, 2022). "Changes in brain insulin levels and IR density, as well as reducing the sensitivity of IRs (i.e., insulin resistance), can lead to changes in insulin signaling." (PMID 36430894, 2022). "Collectively, these data suggested that 1e ameliorated PA-induced insulin resistance in C2C12 muscle cells via the insulin-dependent Akt pathway more effectively than GA." (PMID 35409287, 2022). "Insulin resistance is normally compensated by an adaptive increase in pancreatic β-cell mass together with enhanced glucose-stimulated insulin release." (PMID 35706903, 2022).
Insulin resistance (continued). "Insulin resistance has profound physiological consequences, since insulin largely controls the metabolism of amino acids, glucose and fatty acids in key metabolic organs including liver, muscle, adipose tissue and brain." (PMID 36172277, 2022). "How peripheral insulin resistance and central insulin signaling modulate hippocampal function during aging is an important but unsolved clinical question that requires more studies to differentiate the effects of central from peripheral insulin resistance." (PMID 35707855, 2022). "Overexpression of GLUT4 in the muscles of genetically diabetic mice (db/db) alleviates insulin resistance by raising both basal- and insulin-stimulated glucose transport." (PMID 36144260, 2022). "Glucose was assessed using insulin concentration, following the homeostasis model assessment of insulin resistance (HOMA-IR)." (PMID 36421225, 2022). "Insulin resistance is a pathological condition in which body cells manifest reduced sensitivity to insulin." (PMID 35267895, 2022). "The development of T2D is mainly caused by insufficient insulin secretion by β-cells localized in the pancreas and the state called “insulin resistance”, which is the inability of insulin-sensitive tissues to respond to insulin properly." (PMID 35008906, 2022). "Insulin resistance induced by obesity in the liver characterized by impairment in the ability of insulin to inhibit glucose output, finally resulting in gluconeogenesis." (PMID 36230963, 2022). "Probiotic supplementations, however, improved glycaemic parameters by reducing HOMA-IR, FBG, and fasting insulin, all of which are positive routes toward hepatoprotection against insulin resistance which plays important role in the pathogenesis of NAFLD." (PMID 35479741, 2022). "The skeletal muscle has been demonstrated to be the primary tissue in insulin-stimulated glucose uptake and therefore dysregulation within this tissue is thought to be central to insulin resistance." (PMID 35204022, 2022). "The higher insulin resistance in this group indicated low insulin sensitivity by the target tissues or reduced responsiveness of target tissues to insulin." (PMID 36434695, 2022). "As insulin resistance is characterized by the inability of insulin to induce proper signal transduction leading to impaired insulin-induced vasodilation, we studied the vasorelaxant properties of insulin on Phe-contracted aortic rings." (PMID 36033104, 2022). "The serum ferritin level was positively correlated with the level of insulin resistance and inversely correlated with the insulin level of the patients." (PMID 35736651, 2022). "Supplementation of 2% freeze-dried blueberry powder for 13 weeks in Obese Zucker rats have demonstrated significant reductions in glucose, fasting insulin and insulin resistance, as indicated by the Homeostasis Model Index of Insulin Resistance (HOMA-IR)." (PMID 36112580, 2022). "This accumulation of ectopic fat disrupts organ and tissue function, promoting a state of impaired sensitivity or response to insulin action, i.e., insulin resistance." (PMID 36501139, 2022). "After 20 weeks of SuperJump activity GLP-1 and GIP levels were significantly increased while fasting insulin, glucose, insulin resistance, were significantly reduced." (PMID 35205162, 2022). "T2DM is preceded by a long period of insulin resistance (often obesity related), and only requires exogenous insulin therapy if pancreatic islet reserves are depleted." (PMID 35203115, 2022). "Insulin resistance occurs when insulin’s biological effect on the skeletal muscle, liver, adipose tissue, and other peripheral tissues is less than its expected physiological effect." (PMID 35501770, 2022). "Insulin resistance is a general term that characterizes a low response of adipose tissue, skeletal muscle, liver, and pancreas to insulin action." (PMID 35966520, 2022).
Insulin resistance (continued). "We further examined two indices, HOMA-IR and Matsuda index, reflecting insulin resistance and insulin sensitivity, respectively." (PMID 35578615, 2022). "On the contrary, adipocytes treated with ZF‐EVs displayed a significant decrease in insulin‐stimulated glucose uptake, suggesting that EVs from ZF hepatocytes promote insulin resistance in adipocytes." (PMID 38938664, 2022). "In diabetes, IRS-1 phosphorylation has been established to be related to insulin signal transduction, hence galangin, and pinocembrin reinstate the sensitivity of insulin receptors and diminish insulin resistance." (PMID 36028892, 2022). "The observation that insulin-stimulated GLUT4 dispersal is reduced in insulin resistant models and the behaviour of GLUT4 vesicles adjacent to the PM is modulated in insulin resistance further emphasises the potential importance of PM-associated GLUT4 events." (PMID 35735144, 2022). "In the case of insulin resistance, as insulin sensitivity is compromised there is stimulation of β-cells to secrete increased amounts of insulin than under normal conditions." (PMID 37654824, 2022). "Dysglycemia is often concurrent with insulin resistance and decreased insulin sensitivity; it can inhibit oxidative decomposition and utilization of free fatty acids in the liver and increase triacylglycerol levels." (PMID 36526962, 2022). "Insulin resistance is a condition in which the efficiency of insulin to promote glucose uptake and utilization decreases for various reasons, and the body secretes excessive insulin to produce hyperinsulinemia, which maintains blood glucose stability." (PMID 36246058, 2022). "Resistance to insulin action (insulin resistance) is the fundamental abnormality of MetS, pre-DM, and type 2 DM." (PMID 35052857, 2022). "Of note, insulin resistance in many previous studies was measured by the Homeostatic Model Assessment for Insulin Resistance (HOMA-IR) which requires measurements of fasting insulin and glucose." (PMID 36329456, 2022). "Deterioration in glycemic levels including both insulin resistance and impaired insulin secretion were recently reported upon SARS-CoV-2 infection." (PMID 35215201, 2022). "The HOMA insulin resistance index was also lower (−1.3; 95% CI, −2.2 to −0.3; p < 0.001) and the predicted insulin sensitivity index (PREDIM) increased (0.9; 95% CI, 0.5–1.2; p < 0.001) for the vegan group." (PMID 35406013, 2022). "The fact that this can be observed long before the deterioration of glucose tolerance testifies to the existence of early asymptomatic insulin resistance and the role of insulin in the metabolism of BCAAs." (PMID 36615726, 2022). "Glycemic markers including fasting blood glucose (FBG), hemoglobin A1c (HbA1c), insulin, and Homeostatic Model Assessment for Insulin Resistance (HOMA-IR) are used to monitor glycemic control in clinical practice." (PMID 36704801, 2022). "A genetic aspect to insulin resistance (IR) involves abnormal insulin signaling and leads to type 2 diabetes." (PMID 35163806, 2022). "Conversely, overexpression of SHP2 using adenovectors resulted in glucose intolerance, insulin resistance, and impaired insulin signaling." (PMID 36140242, 2022). "Antidiabetic drugs act on adipose tissue and muscle to enhance insulin sensitivity and target the liver to inhibit glucose production, or stimulate β-cells to release insulin, thereby slowing the development of insulin resistance." (PMID 36230963, 2022). "The first one is the insulin resistant prediabetic stage, in which the main event is the insulin resistance with normoglycemia." (PMID 36465657, 2022). "In breast cancer cells, metformin exerted anticancer effects by changing the metabolic milieu and reducing the circulating insulin levels by improving insulin resistance with reduced insulin/IGF-I receptor-mediated phosphoinositide 3-kinases (PI3K) signaling." (PMID 35455439, 2022).
Insulin resistance (continued). "The evidence of systemic insulin resistance and defective insulin signaling in the brain being common features of AD transformed T2D as an important risk factor for this neurological disorder." (PMID 35406040, 2022). "PC has the effects of delaying cell senescence, inducing adipocyte cell death to reduce local fat deposition, reducing chronic inflammation in adipose tissue, and promoting the conduction of insulin signaling pathways to prevent insulin resistance." (PMID 36291067, 2022). "One of the key characteristics of T2D is beta-cell dysfunction, reducing plasma insulin concentration, which combined with insulin resistance results in hyperglycemia." (PMID 35651975, 2022). "A high consumption of fats of exogenous origin will increase the oxidative capacity of fatty acids, reducing the use of glucose by insulin in the liver and skeletal muscle, resulting in insulin resistance in diabetics." (PMID 36034954, 2022). "Impaired insulin secretion due to dysfunctional pancreatic beta-cells and/or peripheral insulin resistance is established characteristics of T2D, giving dysregulated metabolism of carbohydrates, fatty acids, and protein." (PMID 36501195, 2022). "The development of insulin resistance typically results in a compensatory increase in endogenous insulin production." (PMID 35734406, 2022). "In the same context, insulin resistance is assumed to be induced primarily by irregular hepatic insulin action, in which higher insulin levels are required to control blood glucose levels." (PMID 35337139, 2022). "Fasting insulin, homeostatic model assessment of insulin resistance, BMI, waist circumference, BP, and triglycerides were significantly higher and HDL cholesterol was significantly lower in women with PCOS compared to without PCOS." (PMID 35642189, 2022). "Insulin resistance is characterized by defects of insulin signaling and reduction of glucose uptake in peripheral insulin-sensitive cells or tissues." (PMID 35958293, 2022). "In turn, IR knockout experiments and the use of insulin-re-sensitizing agents confirm that the resolution of insulin resistance restores the impaired activity of PGC-1α, energy metabolism and mitochondrial biogenesis." (PMID 36117625, 2022). "Lastly, higher IL-38 levels were observed to be closely correlated with insulin resistance (INS, CpS, HOMA-IR, and QUICK), liver injury (AST and ALT), and inflammation [IL-6 and 25(OH)D]." (PMID 35948957, 2022). "IGF-1 and insulin have a synergistic effect, possibly indicating the level of insulin resistance in the human body." (PMID 36120463, 2022). "Beta-cell-restricted genetic manipulations that limit HFD-induced beta-cell mass expansion or the amplification of glucose-stimulated insulin secretion (GSIS) have been shown to protect against insulin resistance." (PMID 34823065, 2022). "It is well-known that the autonomic nervous system modulates insulin secretion and plays an essential role in insulin resistance in T2DM." (PMID 36428566, 2022). "Serum ferritin was positively correlated with the degree of insulin resistance and inversely correlated with insulin levels in patients with metabolic syndrome." (PMID 35736651, 2022). "HOMA-IR is the insulin resistance index and is also the gold standard for evaluating insulin sensitivity." (PMID 35371260, 2022). "Adipocyte-specific knock-down of CUL4B-RING E3 ligase (CRL4B), which promotes polyubiquitination and proteasomal degradation of PPARγ, can ameliorate high fat-induced glucose intolerance and insulin resistance, as well as enhance adipocyte insulin sensitivity." (PMID 36551260, 2022). "There is enough evidence to suggest that changes in adipocytokine secretion do contribute to defective insulin production/action and, concomitantly, result in peripheral insulin resistance." (PMID 35629157, 2022).
Insulin resistance (continued). "Consistent with the notion that hyperlipidemia usually occurs in the presence of insulin resistance, insulin levels were more than 3-fold higher in ad libitum fed 16–17-week-old Titan mice." (PMID 35505192, 2022). "Insulin resistance occurs when cells in muscles, body fat and liver resist or ignore the response to insulin released from the pancreas, leading to high blood glucose." (PMID 35154496, 2022). "Differentiating the CNS effects, particularly those related to cognition, due to either high blood glucose or high blood insulin levels can be difficult as both are often present in peripheral insulin resistance." (PMID 35884888, 2022). "T2D is a complex metabolic disorder characterized by hyperglycaemia, insulin resistance or impaired insulin secretion or both." (PMID 35763080, 2022). "Obesity-related pro-inflammatory adipokines, such as leptin, interleukin 6 and tumor necrosis factor a, inhibit normal insulin signaling, leading to insulin resistance and promoting endometrial proliferation." (PMID 35615721, 2022). "Insulin resistance and hyperinsulinemia are important features of diabetes and growing in vitro evidence suggests a direct effect of insulin and insulin-like growth factor 1 (IGF-1) on endometrial cancer." (PMID 35439978, 2022). "Insulin resistance is defined as “a reduced response of targettissues (to insulin),compared with subjects with normalglucose tolerance”." (PMID 35216280, 2022). "In several models of insulin resistance, it has been shown that reduced glucose uptake is due to defects in insulin signaling and is associated with impaired Akt phosphorylation, leading to the development of insulin resistance in obesity and type 2 diabetes." (PMID 35250480, 2022). "The results of model studies of oral zinc supplementation in type 1 and 2 diabetes mellitus in rats showed that it reduces insulin resistance, elevated insulin levels, and the cytotoxic effect of streptozotocin." (PMID 36290631, 2022). "Fasting glucose and insulin measures were used to calculate homeostatic model assessment for insulin resistance (HOMA-IR), a surrogate measure of insulin sensitivity." (PMID 35013420, 2022). "Asian individuals, who exhibit a low insulin secretion ability and insulin resistance with mild obesity, have a T2DM pathophysiology different from that of American and European individuals." (PMID 35115614, 2022). "FOXO proteins can affect both insulin synthesis in pancreatic beta cells and can also affect insulin resistance." (PMID 36232910, 2022). "Abnormal insulin response, insulin resistance and reduced circulating insulin levels were detected in cachectic cancer patients, potentially causing a shift in metabolic balance resulting in elevated lipolysis." (PMID 35646636, 2022). "The concept of insulin resistance has been around since a few decades after the discovery of insulin itself." (PMID 35884888, 2022). "Impairments in this pathway induce insulin resistance (reduced tissue responsiveness to the physiological action of insulin), obesity, and T2D in insulin-sensitive tissues." (PMID 35742902, 2022). "The current results showed that treatment with 50,000 IU of vitamin D for three months increased the sensitivity to insulin levels and significantly reduced the insulin resistance index measured by HOMA-IR." (PMID 36362806, 2022). "Despite this adverse phenotype, fasting insulin levels and insulin resistance are comparatively lower at all ages in obese patients with PWS." (PMID 35774143, 2022). "Different models of insulin resistance induction have been applied to SGBS cells including chronic high insulin and/or glucose or pro-inflammatory factors such as interferon gamma, TNFα, or IL-29." (PMID 35986215, 2022). "While elimination of p21high cells in WAT suppressed SASP phenotypes and improved both glucose tolerance and insulin sensitivity, senolysis targeting of p16high cells to alleviate insulin resistance was less efficient." (PMID 35432205, 2022).